MIR497 (microRNA 497)
Synonyms: hsa-mir-497; MIRN497; mir-497
Gene: MicroRNA gene on chromosome 17 (7,017,911 to 7,018,022, reverse strand). Ensembl gene ENSG00000284027.
Gene Ontology:
Biological process: miRNA-mediated post-transcriptional gene silencing
Cellular component: RISC complex
Homologues: Orthologues: macaque mml-mir-497 (100% identical), chimpanzee MIR497 (97% identical), rabbit MIR497 (90% identical), mouse Mir497 (73% identical), pig ssc-mir-497 (73% identical), rat Mir497 (71% identical), guinea pig MIR497 (61% identical), dog MIR497 (56% identical).
Diseases named in the same sentence as MIR497 in open-access papers:
MIR497 is named in the same sentence as 1 disease in open-access papers, as found by Europe PMC text mining. Sharing a sentence is not in itself a finding about the gene and the disease.
MIR497 shares sentences with these, for which no sentence is quoted: cancer (1 paper).